IL10 (interleukin 10)
Diseases named in the same sentence as IL10 in open-access papers (continued):
Sharing a sentence is not in itself a finding about the gene and the disease.
cervical carcinoma (continued). "Previously, we reported that IL-10 and TGF-β1 are expressed in cervical lesions; therefore, the development of SIL and cervical cancer is preferentially associated with the expression of immunosuppressive cytokines (IL-10 and TGF-β1) and Th2-type cytokines (IL-4/IL-6)." (PMID 24808638, 2014). "Furthermore, the IL-10 rs1800896 gene polymorphism affects carcinoma of the uterine cervix." (PMID 37077342, 2023). "The -592C/A polymorphism of the IL-10 gene may be considered a risk factor for cervical cancer." (PMID 35919032, 2022). "Atopobiaceae (CST IV) were enriched in cLSIL, cHSIL, and cervical carcinoma and positively correlated with IL-1α, IL-4, IL-10, IL-12, IL-36γ, IFN-α2, IFN-γ, and TNF-α in cervicovaginal lavages." (PMID 40362199, 2025). "For instance, it was reported that HPV16 E2 can upregulate the expression of IL-10 in cervical cancer cells, contributing to local immune suppression and aiding viral persistence." (PMID 40002177, 2025). "In cervical cancer, TAMs secrete IL-10, inducing the proliferation of HPV-specific regulatory T cells and suppressing the anti-tumor activity of effector T cells, thereby contributing to adverse prognosis." (PMID 40264780, 2025). "The IL-10 gene promoter exhibits lineage-specific methylation in cervical cancer cell lines, silencing IL-10 production in neoplastic cells, while stromal cells or infiltrating lymphocytes produce IL-10, contributing to local immune suppression." (PMID 41029427, 2025). "In the microenvironment of cervical cancer, expression levels of B7-H3 and B7-H4 positively correlated with the expression levels of IL-10 and TGF-β1, suggesting correlation with the p-JAK2/STAT3 pathway." (PMID 38850312, 2024). "Within the context of cervical cancer, cytokines IL-4 and IL-10 play pivotal roles in modulating immune responses and tumor expansion." (PMID 39207449, 2024). "Further studies with longer follow-up will be necessary to evaluate the association of IL-10 with the persistence of HPV infection, CIN, and cervical cancer in WLHA." (PMID 39007140, 2024). "At diagnosis, our findings showed that plasma levels of sHLA-G and IL-5, IL-6, IL-8, IL-10, IL-17, and were significantly increased in patients with cervical cancer." (PMID 36053326, 2023). "Tumor-derived thymic stromal lymphopoietin (TSLP) can activate eosinophil to increase the expression of IL-4, IL-5, IL-10 and IL-13, and promote the proliferation of cervical cancer cells." (PMID 36874093, 2023). "Cross-talk between Tim+Treg cells and Galectin-9+monocyte in the HPV-related cervical cancer stimulates the secretion of IL-10 and TGF-β, whereas it prevents IFN and IL-12 genes expression." (PMID 35632488, 2022). "Generally, it seems that in the case of cervical cancer, dampening IL-10 would help the proliferation of more CTLs in the tumor microenvironment and thereby enhancement of tumor regression." (PMID 35752792, 2022). "Circ_ZFR regulated paclitaxel resistance via sponging miR-944 and upregulating IL-10 in cervical cancer." (PMID 36438563, 2022). "A case–control study that compares the ratio of Breg cells in cervical cancer patients and healthy people reveals the increasing number of Breg cells and IL-10." (PMID 35632488, 2022). "An altered balance in IL-12p70 and IL-10 production can weaken T cell proliferation in cervical cancer." (PMID 33671013, 2021). "In cervical lesions, it has been reported that the amount of IL-10 in TME was associated with the type of HPV infection and the degree of progression from lesions to cervical cancer." (PMID 34717710, 2021). "The immunosuppressive cytokines such as IL-4 and IL-10 have been long investigated in cervical carcinoma, while the IL-1 receptor antagonist has been investigated in relation to epilepsy." (PMID 32899735, 2020).
cervical carcinoma (continued). "for example: In cervical cancer, IL-10 can interfere with the differentiation of dendritic cells and thus play a strong immunosuppressive effect,TGF—β 1 can inhibit T cell proliferation and attenuate immune response." (PMID 32843657, 2020). "The IL-10 level in cervical cancer patients was significantly higher than that in the CIN group and the healthy control group (P < 0.05)." (PMID 31316301, 2019). "At the same time, we found that the percentage of Bregs and IL-10 increased with the degree of FIGO stages of cervical cancer." (PMID 31316301, 2019). "The percentage of CD19+CD5+CD1d+ Breg cells and the level of IL-10 of patients with cervical cancer or CIN were significantly higher than those in the control group (P < 0.05)." (PMID 31316301, 2019). "By comparing with the healthy controls and the CIN group, we found that the Breg cells and IL-10 of cervical cancer patients were significantly increased and that they were positively correlated with each other." (PMID 31316301, 2019). "The changes of Bregs and IL-10 before and after the surgery were investigated in 57 patients who underwent radical resection of cervical cancer." (PMID 31316301, 2019). "The results showed that with the stage of cervical cancer advanced, the IL-10 level gradually increased." (PMID 31316301, 2019). "HPV-transformed cell lines and tissues studied from patients with cervical cancer and high-grade CINs have demonstrated that the soluble mediators, IL-10, TGF-β and prostaglandins (PG), play a key role in the establishment of an immunosuppressive milieu." (PMID 29179871, 2017). "The present study shows that the concentrations of TGF-β and IL-10 are elevated while that of IFN-γ is reduced in cervical cancer." (PMID 27721577, 2016). "The levels of IL-1beta, IL-2, TNF-alpha, and IL-10 were negatively correlated with the percentages of CD4+NKG2D+ T cells in patients with cervical carcinoma." (PMID 26486970, 2015). "Serum levels of IL-10 and its expression in tumor cells are elevated in patients with cervical cancer." (PMID 23936772, 2013). "In patients affected by HPV-related cervical cancer, apoptotic cells originated by the epithelium turnover are phagocytosed by dendritic cells that release immunosuppressive cytokines as TGFb, IL10, and IL13." (PMID 24455729, 2013). "Collectively, the expression levels of TGF-β, IFN-γ, IL-6, IL-10, IL-17 and IL-23 were up-regulated in cervical cancer patients." (PMID 23587428, 2013). "We found that levels of TGF-β, IL-6, IL-10, IL −17 and IL-23 in patients with cervical cancer and cervical CIN were significantly higher than those in the control group." (PMID 23587428, 2013). "Expression levels of TGF-β, IFN-γ, IL-6, IL-10, IL-17 and IL-23 are elevated in cervical cancer patients and CIN patients." (PMID 23587428, 2013). "The relatively low IL-10 expression in HPV16-infected SiHa cervical cancer cells was used as a positive control." (PMID 23118878, 2012). "In cervical cancer patients, IL-10 is secreted by regulatory CD4 lymphocytes stimulated with HPV antigens." (PMID 20525400, 2010). "Cluster of Differentiation-4(CD4),Cluster of Differentiation-8(CD8), and interleukin-10 (IL-10) have long been considered to be related to cervical cancer, but the exact relationship remains unclear." (PMID 41142594, 2025). "Interestingly, the HCMV UL111A gene encodes cmvIL-10, a viral homolog of human IL-10, which promotes monocyte conversion to an immunosuppressive phenotype and activates STAT3 in cervical cancer cells." (PMID 40002177, 2025). "Moreover, low-dose naltrexone decreases the number of M2-type macrophages and reduces serum IL-10 secretion, thereby inhibiting cervical cancer progression." (PMID 40264780, 2025). "However, further studies with longer follow-up will be needed to evaluate the association of IL-10 with HPV infection, CIN, and cervical cancer in WLHA." (PMID 39007140, 2024).
cervical carcinoma (continued). "Together, these data indicated that increased MDSCs accumulation, IL-10 or BAFF expression may participate in cervical cancer progression." (PMID 35725835, 2023). "Regardless of time (pre- or postoperative), a positive correlation was observed between plasma levels of IL-6 and IL-10 (P < 0.05), suggesting that these two cytokines may play a key role in immune regulation in cervical cancer." (PMID 36053326, 2023). "Furthermore, we found that the concentration of IL-10 in the peripheral blood serum of patients with cervical cancer was significantly higher than that with benign tumors (313.8 ± 70.76, n = 20 vs. 40.36 ± 11.51, n = 25, p < 0.001)." (PMID 35725835, 2023). "We also analyzed the correlation of ITGA5 with anti‐angiogenesis genes THBS2, PTEN, SERPZNF1, and IL‐10 in cervical cancer based on TCGA dataset, but the correlations were rather modest as the R values ranged between −0.011 and 0.16, though the p values were less than 0.05." (PMID 36999964, 2023). "Furthermore, owing to the role of IL-10 cytokine in the progression of HPV-positive cervical cancer cells, we assessed if the IL-10 blockade improved the efficacy of the E7&IL-24 candidate vaccine against TC-1 tumor cells." (PMID 35752792, 2022). "In another in vitro co-culture system, Bregs sorted from cervical cancer patients secreted IL-10 to decrease the percentage of CD8+ T cells, which produced perforin and GrB, whereas the addition of anti-IL-10 antibodies restored the level of these CD8+ T cells." (PMID 33193391, 2020). "The results showed that the addition of cervical cancer cell supernatant during the differentiation of monocytes into macrophages inhibited the expression of M1 cytokines such as IL‐1β and IL‐6 and promoted M2 cytokines such as IL‐10 and CCL22 expression." (PMID 31943744, 2020). "Notably, IL-10 has also been reported to contribute to tumorigenesis in multiple human malignancies, including colorectal and cervical carcinoma." (PMID 32348468, 2020). "Breg cells and the IL-10 level were positively correlated in cervical cancer patients (r = 0.516)." (PMID 31316301, 2019). "We further analyzed the correlation of Bregs with IL-10 in cervical cancer patients." (PMID 31316301, 2019). "Actually, IL10 is used in combination with IL2 in the treatment of cervical cancer." (PMID 30622662, 2018). "In contrast, other studies reported a negative association between the IL-10–1082A > G polymorphism and cervical cancer risk." (PMID 29552317, 2018). "Since it was reported that IL10 plays a role in maintenance of Tregs and immunosuppression in cervical cancer, this correlation might be important in understanding the mechanism." (PMID 28670312, 2017). "Moreover, immature stromal dendritic cells expressing IL-10 are more numerous in cervical cancer than in normal cervix and cervical intraepithelial neoplasia." (PMID 28854209, 2017). "It is therefore possible that the heterogeneous effect of IL10 polymorphisms in HPV and cervical cancer might be tied to the stage of lesions." (PMID 28280748, 2017). "Additionally, in vitro examination of HPV-positive cervical cancer cell lines demonstrated that IL-10 and TGF-β derived from cancer cells suppress MHC-I expression in tumor cells, preventing CTL-mediated clearance of HPV-transformed KCs." (PMID 29179871, 2017). "The results of relevance between changes of PD-1/PD-L1 and Treg cells demonstrate that PD-1/PD-L1 signaling pathway may exert its immune suppression effect via Treg cells and its factors TGF-β and IL-10, leading to the occurrence of cervical cancer." (PMID 27721577, 2016). "Our results demonstrate that PD-1/PD-L pathway inhibits T lymphocyte proliferation, promotes the secretion of TGF-β and IL-10, and results in the proliferation of differentiation of Tregs in cervical cancer microenvironment, finally leading to the escape of tumor cells from immune system." (PMID 27721577, 2016).
cervical carcinoma (continued). "HMGB1, forkhead/winged helix transcription factor p3 (Foxp3), IL-2, and IL-10 protein expression was analyzed in 100 cervical tissue samples including cervical cancer, cervical intraepithelial neoplasia (CIN), and healthy control samples using immunohistochemistry." (PMID 24837834, 2014). "The data shown here suggest that HMGB1 may directly activate Tregs by binding to RAGE, which promotes IL-10 production in cervical cancer or helps to shift Th1 cells to Th2 cells and assist in tumor evasion and development." (PMID 24837834, 2014). "Additionally, IL-10 expression was decreased by HPV16 or18 E6-knockdown in SiHa or HeLa cervical cancer cells and increased by HPV16 E6 overexpression C33A cervical cancer cells." (PMID 23118878, 2012). "Moreover, women with cervical cancer have circulating regulatory T cells that inhibit effector response and secrete IL-10 upon antigen stimulation." (PMID 20525400, 2010). "Lower serum concentrations of IFN-y and higher serum concentrations of IL-10 were found in women with cervical cancer or CIN, suggesting that an imbalance between Th1/Th2 and Th17/Treg cells may be responsible for the persistent HPV infection and progression to cancer." (PMID 39007140, 2024). "The results of both studies further showed that Interleukin-10 (IL-10) expression was also significantly increased in cervical cancer tissues, which supports a shift toward a Th2 cytokine microenvironment; this in turn may promote local immunosuppression by upregulating HLA-G expression." (PMID 32670296, 2020). "However, little is known about the role of IL-10 in metastatic cervical cancer." (PMID 28854209, 2017). "The staining of TGFβ, PD-L1, IL-10, FOXP3, IL-17, and MIF was cytoplasmic and present in 25%, 9.4%, 56.2%, 7.2%, 76.3%, 86.1%, and 85.2%, respectively, of the cervical cancer cases." (PMID 39061137, 2024). "Elevated levels of IL-4, IL-10, and TGF-βI have been observed in the serum of cervical cancer patients, whereas INF-γ concentrations are diminished in this population." (PMID 38881859, 2024). "In this study, our findings showed that preoperation plasma levels of sHLA-G and the cytokines IL-6, IL-10, and IFN-γ in cervical cancer patients had a good discriminatory effect between cervical cancer patients and healthy women." (PMID 36053326, 2023). "The level of cytokines such as IL-6, IL-10, IL-8, TNF-α, and VEGF can be co-related with disease progression in ovarian, breast, and cervical carcinoma." (PMID 37746258, 2023). "We can still identify some genes related to cervical cancer progression from the samples of the two patients after treatment, including ATF3, GPX3, IL10, IL6, RAD51AP1, MGMT, WWOX." (PMID 37914994, 2023). "In content of cervical cancer, TME affecting carcinogenesis (after HPV infection) by several ways including locally increased levels of cytokines, particularly TGF-β1 and IL-10." (PMID 33802621, 2021). "Recent studies have shown that in cervical cancer, Poly(I:C), an adjuvant for cancer vaccine, may act through the NF-κB signaling pathway to promote the expression of M1-type cytokines (such as IL-1β and IL-6) and inhibit the expression of M2-type cytokines (such as IL-10 and CCL22)." (PMID 34717710, 2021). "poly(I:C)‐stimulated supernatant of cervical cancer cells promoted M1‐type cytokine IL‐1β and IL‐6 expression of THP‐1–derived macrophages, but inhibited the expression of M2‐type cytokine, IL‐10 and CCL22." (PMID 31943744, 2020). "We found that the levels of IL-10 in culture supernatant of Bregs treated with CpG were higher than those of non-Bregs, indicating that Breg cells and non-Breg cells are successfully identified and that Breg cells in cervical cancer patients may exert their regulatory effects through IL-10." (PMID 31316301, 2019). "In order to understand the role of Bregs in patients with cervical cancer, we analyzed CD1d+CD5+CD19+ Breg cells and the level of IL-10." (PMID 31316301, 2019).
cervical carcinoma (continued). "On the other hand, cervical cancer cells can secrete a series of molecules such as PEG2, IL-6, CCL2, and IL-10 that differentiate and activate M2-like macrophages." (PMID 31842422, 2019). "In cervical cancer, HPV up-regulated interleukin 10 (IL-10) and transforming growth factor (TGF)-β to avoid the antitumor immune responses." (PMID 31001266, 2019). "This study investigated serum interleukin-10 (IL-10) levels, changes in peripheral blood CD4+CD25+ regulatory T cell (PBCDT) ratios, and the prognosis of cervical cancer (CC) patients." (PMID 30517305, 2018). "High expression of PD-1 on Treg cells in cervical cancer patients facilitated the production of TGF-β and IL-10 but inhibited the production of IFN-γ." (PMID 27721577, 2016). "The data showed that the levels of TGF-β, IL-10, and IFN-γ were significantly different among cervical cancer group, CIN group, and control group (P < 0.05)." (PMID 27721577, 2016). "In summary, our findings demonstrate that elevated levels of PD-1/PD-L1, TGF-β, and IL-10 in peripheral blood of cervical cancer patients may negatively regulate immune response against cervical cancer cells and contribute to the progression of cervical cancer." (PMID 27721577, 2016). "CBA assay showed that the levels of IL-10 and TGF-β in lymphocyte culture supernatants from cervical cancer group and CIN group were significantly higher than those from control (P < 0.05)." (PMID 27721577, 2016). "In cervical cancer patients, the levels of TGF-β and IL-10 were significantly enhanced, and the level of IFN-γ was significantly reduced." (PMID 27721577, 2016). "IL-10 mRNA/protein is augmented in cervical cancer, but HeLa cells were reported not to express IL-10." (PMID 39682467, 2024). "In a study of clinical specimens, we found that the accumulation of MDSCs in patients with cervical cancer was accompanied by high expression of B cell activating factor (BAFF) on the surface and high expression of interleukin (IL)-10-producing B cells (B10) in vivo." (PMID 35725835, 2023). "In cervical cancer tissues, the expression levels of IL10 and Ki-67 increased accordingly when the HPV infection rate increased, so the detection of IL10, KI67 expression and HPV infection rate can provide reference for the diagnosis of cervical cancer." (PMID 37914994, 2023). "Our experiments demonstrate that EVs from cervical cancer patients after radiotherapy contributed to the M2-like to M1-like phenotype transition (increased expression of CCR7, TNFα and iNOS, and decreased expression of CD163 and IL-10)." (PMID 35062905, 2022). "In addition, we found that ICA inhibited cervical cancer SiHa cells proliferation, migration, invasion, and the expression levels of TGF-β1, TNF-α, IL-6, IL-17A, and IL-10, as well as promoted cell apoptosis." (PMID 33849528, 2021). "As STAT3 can be activated by several soluble factors in cervical cancer cells, such as OSM, EGF and IL-10, it is possible that the IL-6 low cancers might be dependent on these additional cytokines to maintain active STAT3." (PMID 31226168, 2019). "The possible DC suppressive effect of IL-10 and TGF-β in a chronic HPV-infected local microenvironment is evidenced by a correlation between elevated levels of TGF-β and IL-10 positive Treg cells, regulatory DCs and impaired CTL responses in cervical cancer epithelium compared to normal cervix." (PMID 29179871, 2017). "Moreover, the increase in the expression of IL-10 gene in people infected with HPV was demonstrated in the case of other types of tumours, such as cervical cancer." (PMID 27547238, 2016). "Previous studies on cervical cancer indicated that M2-like macrophages could decrease the presence of HPV16 E7 specific CD8+ T cells by diminishing HLA-DR expression and increasing the expression of either IL-10 or CSF1R." (PMID 31842422, 2019). "And E6 protein could stimulate IL-10 expression in both OSCC cells and cervical cancer cells." (PMID 31001266, 2019).